GFAP (glial fibrillary acidic protein)
Diseases named in the same sentence as GFAP in open-access papers (continued):
Sharing a sentence is not in itself a finding about the gene and the disease.
COVID-19 (108 papers, 2020 to 2026). A disease caused by infection with severe acute respiratory syndrome coronavirus 2. "Post-COVID-19 decreased GFAP and NfL were associated with peripheral symptoms of N-PASC, but not with increased pTau-181." (PMID 41494242, 2026). "Global cognitive deficits were found in patients 1 year after COVID-19 hospitalization, which was associated with elevated serum NfL and GFAP." (PMID 41020593, 2025). "Evidence from a recent study on COVID-19 patients showed that higher GFAP levels at follow-up were associated with mild cognitive dysfunction." (PMID 41502564, 2025). "In contrast, the elevated serum GFAP in hospitalized COVID-19 patients was reportedly associated with long-term neurological symptoms (monitored up to 1 year after hospital admission)." (PMID 39451987, 2024). "Consistent with our findings, a recent study found that in a sample of 175 patients admitted with COVID-19, the NfL and GFAP were associated with elevations of pro-inflammatory cytokines and the presence of auto-antibodies." (PMID 39125829, 2024). "Regarding GFAP, increased levels have been previously associated to critical and lethal outcomes in severe COVID-19." (PMID 37996731, 2024). "Serum GFAP showed a significant association with the severity of COVID-19 infection, and both NfL and GFAP predicted COVID-19-associated mortality in hospitalized patients." (PMID 37958721, 2023). "Elevated NfL and GFAP blood levels have been reported in COVID-19, and higher levels are associated with severe disease." (PMID 37768470, 2023). "Increased concentrations of GFAP in patients with COVID-19 are found to increase the mortality risk and can be used as a possible biomarker for COVID-19 severity." (PMID 37834358, 2023). "Pooled SMDs were computed for 13 studies in the analysis of the association between GFAP levels in patients with COVID-19 and healthy controls, comprising a total of 1896 participants (1413 COVID-19 patients and 483 healthy controls)." (PMID 37958721, 2023). "In this context, previous studies of patients with COVID-19 at acute phase demonstrated from elevations in serum of NfL and GFAP also associated with elevations of pro-inflammatory cytokines." (PMID 36769057, 2023). "To determine the association of GFAP and NfL with COVID-19, we pooled the SMD from included studies." (PMID 37958721, 2023). "The present meta-analysis revealed a significant association between COVID-19 and elevated levels of GFAP and NfL." (PMID 37958721, 2023). "An increased plasma concentration of glial fibrillary acidic protein (GFAP), a hallmark of astrocyte activation, is commonly detected in patients with moderate and severe COVID-19." (PMID 36089575, 2022). "Recently, serum GFAP levels were found to be higher in COVID-19-associated CINM than other critically unwell COVID-19 patients." (PMID 34661878, 2021). "Similarly, meta-analysis has demonstrated higher NfL and GFAP in COVID-19 patients compared with healthy controls, and an association between these serum brain injury markers and COVID-19 severity and poorer outcomes." (PMID 39312956, 2025). "In addition, another study concluded that patient age and levels of serum GFAP were significant predictors of in-hospital COVID-19-associated mortality." (PMID 37958721, 2023). "This implies that increased GFAP could indicate the severity of COVID-19-associated neurological damage." (PMID 37958721, 2023). "Recent studies have also related serum biomarkers to COVID-19 severity and mortality, including neurofilament light chain (NfL), glial fibrillary acidic protein (GFAp), total TAU (Microtubule-Associated Protein Tau, MAPT), and Ubiquitin carboxy-terminal hydrolase L1 (UCH-L1)." (PMID 36362378, 2022). "Biomarkers of neurodegeneration in the cerebrospinal fluid (CSF), such as tau proteins, neurofilament light chain protein (NfL), and glial fibrillary acidic protein (GFAp), are increased in COVID-19 patients and associated both with neurological symptoms and disease severity." (PMID 33673697, 2021).
COVID-19 (continued). "An alternative explanation may be that in some individuals, COVID-19-related neuroinflammation restricted glymphatic clearance causing increased aggregation of larger proteins (like NfL or GFAP: width ∼10 nm) but potentially allowing smaller proteins like pTau-181 (5 nm) to pass through unimpeded." (PMID 41494242, 2026). "Finally, among the 15 COVID-19 patients with severe NS on hospital admission requiring PL for diagnostic purposes, an investigation of neuronal and astrocyte damage (NfL and GFAP), myeloid activation (sCD163) and BBB alteration biomarkers (MMP-9 and TIMP-1) on CSF samples was performed." (PMID 37759493, 2023). "One potentially paradoxical finding was that higher pre-COVID-19 NfL was weakly associated with higher risk of N-PASC but that individuals with N-PASC then saw decreased NfL and GFAP following COVID-19 onset appears paradoxical." (PMID 41494242, 2026). "Several follow-up studies covering a time frame from 24 to 48 weeks in COVID-19 patients also reported normalized levels of S100β, GFAP, and NfL." (PMID 41516418, 2026). "Markers like NfL, Glial fibrillary acidic protein (GFAP and Total Tau protein were confirmed to be increased in 24 patients hospitalized after COVID-19; these markers indicate axonal injury, astrocyte injury and neuronal degeneration." (PMID 41561654, 2026). "Their results are confirmed by Needham, who compared biomarkers in COVID-19 patients to patients with influenza and found similar concentrations of GFAP, NfL and Tau protein." (PMID 39352661, 2025). "Several authors reported elevated GFAP levels in COVID-19 patients with encephalopathy or neurological symptoms." (PMID 39352661, 2025). "The concentration of NfL and GFAP in serum correlates with the World Health Organization’s COVID-19 severity scale." (PMID 41020593, 2025). "In COVID-19 patients experiencing delirium, levels of GFAP and MMP-9 were significantly higher compared to those without delirium." (PMID 39352661, 2025). "Our findings corroborate previous studies that have also investigated NfL and GFAP levels in severe and mild COVID-19 patients in comparison to health control individuals." (PMID 37996731, 2024). "Among COVID-19-positive subjects (severe versus mild COVID-19), GFAP, NfL, and UCH-L1 presented statistical significance difference (p ≤ 0.01), but not total TAU." (PMID 37996731, 2024). "Different from our findings, a previous analysis of 405 mild COVID-19 adolescents and young adult subjects showed significant difference between NfL and GFAP levels when these were compared to health controls." (PMID 37996731, 2024). "As NfL, GFAP, UCHL-1, and Tau protein are associated with senescence, the statistical analysis among severe COVID-19, mild COVID-19, and health control group biomarkers was matched by decade of life." (PMID 37996731, 2024). "Sholl analysis of GFAP immunostained sections revealed an increase in arbor complexity in peri-vascular astrocytes in DS and AD COVID-19 positive cases." (PMID 38801558, 2024). "To date, studies on astrocyte-related biomarkers in subjects with long COVID-19 have mostly focused on the assessment of serum GFAP levels and produced conflicting outcomes." (PMID 39451987, 2024). "Markers of brain injury, including neurofilament light chain (NFL), indicative of axonal damage, and glial fibrillary acidic protein (GFAP), a marker of astrocyte reactivity, were shown to be elevated in serum of COVID-19 patients." (PMID 39720706, 2024). "Furthermore, the association between GFAP and COVID-19-related neurological symptoms also represents a matter of debate, which might be related to the characteristics of neurological manifestations (onset time and numbers/types of symptoms) and/or sampling time." (PMID 39451987, 2024).
COVID-19 (continued). "However, such radial perivascular enhancement pattern was also observed in other diseases with negative GFAP-IgG, such as peripheral lymphoma, meningoencephalitis, and coronavirus disease 2019-associated acute disseminated encephalomyelitis." (PMID 38585352, 2024). "Neurofilament light chain (NfL) and glial fibrillary acidic protein (GFAP) are increased in acute COVID-19." (PMID 38438479, 2024). "This is the first Brazilian study considering mild and severe COVID-19 patients investigated simultaneously by four biomarkers (NfL, GFAP, TAU, and UCH-L1), biochemical parameters, viral load, comorbidities, and outcome analysis." (PMID 37996731, 2024). "In brain samples from deceased patients with acute COVID-19, significant alterations in various astrocyte features, including increased GFAP immunoreactivity and astrocytosis, were observed." (PMID 39451987, 2024). "Studies, including our own, have observed neuroinflammation and apoptosis in reactive astrocytes, indicated by increased glial fibrillary acidic protein (GFAP), an astrocyte-specific brain injury marker, in postmortem brain tissues from COVID-19 individuals." (PMID 38251382, 2024). "Nevertheless, many reports pointed towards an increase in the circulating markers of astrocyte activation, namely S100B and GFAP, during the acute COVID-19 phase." (PMID 39451987, 2024). "Our overall pooled results showed that the level of GFAP was significantly higher in patients with COVID-19 than in healthy controls." (PMID 37958721, 2023). "NfL and GFAP levels in our age-matched controls were also significantly lower than in critical COVID-19." (PMID 37768470, 2023). "For instance, elevated GFAP was found in the white matter of a COVID-19 patient, with encephalomyelitis-like brain damage, oligodendrocytic apoptosis and axonal injuries." (PMID 35922744, 2023). "In any case, altogether, these studies indicate that blood concentrations of GFAP, NfL and T-tau increase with disease severity during the acute phase of COVID-19." (PMID 36769057, 2023). "In the 21 collected studies, it was found that COVID-19 patients had significantly higher levels of pooled GFAP (SMD = 0.52; 95% CI: 0.31, 0.73; p ≤ 0.001) and NfL (SMD = 0.60; 95% CI: 0.37, 0.82; p ≤ 0.001) when compared to the healthy controls." (PMID 37958721, 2023). "A comprehensive search of various databases was conducted until 18 August 2023, to find studies reporting GFAP and NfL blood levels in COVID-19 patients with neurological complications." (PMID 37958721, 2023). "RE method was applied to calculate the pooled SMD of GFAP in the COVID-19 group when compared to the healthy controls with significant heterogeneity (I2: 66%; p ≤ 0.001)." (PMID 37958721, 2023). "The overall pooled SMD value of GFAP indicated a significant increase in patients with COVID-19 when compared to the healthy controls (Z = 4.91; p ≤ 0.001)." (PMID 37958721, 2023). "Their research team discovered notable increases in serum T-tau, P-tau 181, glial fibrillary acidic protein (GFAP), and neurofilament light chain (NfL) levels in individuals with COVID-19-induced encephalopathy." (PMID 38187359, 2023). "Demonstrably, NfL and GFAP were found to be elevated in deceased hospitalized COVID-19 patients and were higher in this cohort when compared to convalescent patients." (PMID 37545721, 2023). "The NfL and GFAP levels in critical COVID-19 in this study are within previously suggested reference intervals in healthy individuals." (PMID 37768470, 2023). "The glial fibrillary acidic protein (GFAP) staining revealed reactive gliosis in 56.3% of COVID-19 patients (9/16) in contrast to controls (40%, 2/6)." (PMID 36855168, 2023). "For the meta-analysis of pooled GFAP, 13 studies with a total of 1896 participants (1413 COVID-19 patients and 483 healthy controls) were included." (PMID 37958721, 2023).
COVID-19 (continued). "Patients with COVID-19 had significantly higher plasma concentrations of GFAP (160%; p < 0.001), NfL (100%; p = 0.015) and T-tau (195%; p = 0.001) than controls." (PMID 36769057, 2023). "At Tpost, the longitudinal evaluation performed on 77 COVID-19 patients showed a significant reduction in plasma levels of NfL, GFAP and sCD163 compared to baseline (p < 0.0001, p < 0.0001 and p = 0.0413, respectively)." (PMID 37759493, 2023). "Different studies revealed that levels of GFAP significantly increased in COVID-19 patients with fatal outcomes." (PMID 37958721, 2023). "Four studies that reported GFAP levels in COVID-19 patients with mild disease and healthy controls were included in the comparison of GFAP levels between patients with mild COVID-19 and healthy controls." (PMID 37958721, 2023). "At baseline, higher plasma levels of NfL, GFAP and sCD163 in COVID-19 patients compared to HD were observed (p < 0.0001, p < 0.0001 and p < 0.0001, respectively), especially in those with severe COVID-19 (p < 0.0001, p < 0.0001 and p < 0.0001, respectively)." (PMID 37759493, 2023). "This is relevant, as in two of three COVID-19 cases we observed GFAP+GAL3+ cells accumulating close to enlarged perivascular spaces (d′) indicative for vasogenic edema due to leakage of blood products." (PMID 38066208, 2023). "Elevated serum/plasma NfL and GFAP levels have been consistently found across patients hospitalized with COVID-19, in a severity-dependent manner, particularly associated with an unfavorable short-term outcome." (PMID 36769057, 2023). "The majority of the studies included in our analysis showed significantly elevated GFAP levels in COVID-19 patients compared to healthy controls, while some studies demonstrated contradictory findings." (PMID 37958721, 2023). "Overall, plasma biomarkers of brain injury, NFL and GFAP, as well as monocyte/macrophage activation markers have been found to be increased in a severity-dependent manner in hospitalized COVID-19 patients." (PMID 37759493, 2023). "Some studies further suggested that COVID-19 patients have chronically elevated levels of neuroinflammatory factors such as blood GFAP and MMP-9." (PMID 38058998, 2023). "It showed that the levels of GFAP and NfL were elevated in COVID-19 patients when compared to healthy controls, indicating the presence of neurological injury." (PMID 37958721, 2023). "A previous longitudinal study also demonstrated that after six months, NfL and GFAP concentrations—which were elevated in the acute phase of patients suffering COVID-19—returned to normal." (PMID 36769057, 2023). "Finally, positive correlations between the CSF and plasma levels of NfL and GFAP in COVID-19 patients with severe NS on hospital admission, validate their plasma assessment as a less-invasive biomarker for diagnosis, prognosis and monitoring of CNS damage associated with COVID-19." (PMID 37759493, 2023). "The fixed-effects model showed that moderate COVID-19 patients had higher levels of pooled GFAP when compared to the healthy controls (SMD = 0.83; 95% CI: 0.63, 1.02; Z = 8.16; p ≤ 0.001; I2: 0%) (the third panel from the top)." (PMID 37958721, 2023). "GFAP and NfL levels were estimated between COVID-19 patients and healthy controls, and meta-analyses were performed using RevMan 5.4 software for analysis." (PMID 37958721, 2023). "In COVID-19-related acute necrotising encephalopathy virus was detected in the CSF, together with extremely high levels of NfL and GFAP, 19 days after the onset of the symptoms and even after testing negative twice." (PMID 35922744, 2023). "Subgroup analysis was conducted to explore the overall pooled SMD of GFAP between COVID-19 patients and healthy controls based on the study design." (PMID 37958721, 2023). "Fixed-effects meta-analysis of the overall pooled GFAP revealed a significant difference between patients with severe COVID-19 and healthy controls (SMD = 1.00; 95% CI: 0.81, 1.18; Z = 10.57; p ≤ 0.001; I2: 0.0%)." (PMID 37958721, 2023).
COVID-19 (continued). "Among 13 studies, there were five studies included in the meta-analysis of the relationship between GFAP and the severity of COVID-19 (mild, moderate, and severe) with 131, 188, and 246 patients with mild, moderate, and severe diseases, respectively." (PMID 37958721, 2023). "In conclusion, our data, together with previous reports, served to demonstrate that, when compared with control levels, increased plasma GFAP, NfL and T-tau in COVID-19 patients in the acute phase of infection are indicative of CNS vulnerability." (PMID 36769057, 2023). "At baseline, in COVID-19 patients with NS, positive correlations between CSF levels of sCD163 and CSF levels of NfL (ρ = 0.7536, p = 0.0017) and GFAP were observed (ρ = 0.7036, p = 0.0045)." (PMID 37759493, 2023). "NF-L and GFAP were significantly elevated in all hospitalized patients (COVID-19 and Controls) who developed long-term neurological symptoms after adjustment for age and disease severity." (PMID 35937088, 2022). "Circulating neural injury markers GFAP and NFL levels were higher in patients with COVID-19 relative to non-COVID-19 controls in the patients receiving ICU level care (GFAP; p = 0.005, NFL; p = 0.009)." (PMID 35937088, 2022). "GFAP is present in COVID-19 patient’s plasma, and its levels are directly correlated with the severity of the disease." (PMID 34714382, 2022). "During hospitalization, sera from patients with COVID-19 demonstrated elevations of NfL and GFAP in a severity-dependent manner, with evidence of ongoing active brain injury at follow-up 4 months later." (PMID 36065116, 2022). "Elevated levels of glial fibrillary acidic protein (GFAP) were noted in COVID-19 patients which is a marker for astrogliosis." (PMID 36353605, 2022). "There is evidence of reactive astrogliosis in COVID-19, accompanied by a significant increase in the plasma levels of the astrocyte-specific protein, glial fibrillary acidic protein (GFAP), in patients with moderate to severe COVID-19." (PMID 35890062, 2022). "High blood GFAP is a marker of structural damage in the acute phase of brain injury and a severity-dependent increase has been detected in COVID-19 patients." (PMID 36591311, 2022). "Conversely, in a separate study on COVID-19 patients, GFAP levels were elevated in comparison to controls, but declined after a mean period of 11.4 days." (PMID 36363686, 2022). "Elevated GFAP plasma levels have been reported in COVID-19 patients and were in line with neuropathological data indicating post-mortem evidence of BBB disruption and gliosis." (PMID 36591311, 2022). "Patients with moderate to severe COVID-19 are often characterized by the presence of elevated plasma levels of glial fibrillary acidic protein (GFAP), which is a biochemical indicator of astrocytic activation." (PMID 36359807, 2022). "In general, closer to the optic nerve, the GFAP immunoreactivity was increased in the COVID-19 patients compared to their age-matched controls." (PMID 34714382, 2022). "It has also been reported that CNS injuries are accompanied by an elevated plasma level of GFAP in moderate and severe COVID-19 patients." (PMID 35672716, 2022). "Another study reported that GFAP was increased in both moderate and severe COVID-19 cases, whereas serum NfL was increased only in severe cases compared to controls." (PMID 35572561, 2022). "Results of quantitative image analysis of GFAP- and HLA-DR-staining of COVID-19 patients and controls." (PMID 35785352, 2022). "This supports that GFAP correlates with disease severity, as it was found at significantly higher levels in COVID-19 patients who died during hospitalization when compared to those who survived." (PMID 36268187, 2022). "In the present study, we demonstrated that there was no significant dynamic of brain injury biomarkers UCH-L1 and GFAP in a 2-week period of ICU stay in male patients with a severe form of COVID-19." (PMID 36363686, 2022).